IMMP2L (inner mitochondrial membrane peptidase subunit 2)
Diseases named in the same sentence as IMMP2L in open-access papers (continued):
Sharing a sentence is not in itself a finding about the gene and the disease.
neurodevelopmental disorder (8 papers, 2014 to 2025). A behavioral and cognitive disorder with onset during the developmental period that involves impaired or aberrant development of intellectual, motor, or social functions. "Larger studies, however, indicate that the frequency of IMMP2L deletions (inclusive of exon sequence) in ‘neurotypical’ control populations is often higher (between 0.1% and 1.85%) than those associated with ASD (between 0.27% and 1.54%) and other neurodevelopmental disorders." (PMID 37761857, 2023). "We present the clinical and molecular description of four unrelated patients affected by neurodevelopmental disorders and overlapping 7q31.1 microdeletion/microduplication, identified by array-CGH and involving only part of the IMMP2L gene." (PMID 25478008, 2014). "High relative incidence of heterozygous intragenic deletions within IMMP2L have also been identified in ASD and in normal ‘neurotypical’ populations casting uncertainty on their role if any in ASD or other related neurodevelopmental disorders such as GTS and ADHD." (PMID 37761857, 2023).
cancer (4 papers, 2012 to 2022). A tumor composed of atypical neoplastic, often pleomorphic cells that invade other tissues. "Interestingly, most of these common candidates are large cancer genes within fragile sites, such as FHIT, WWOX, CCSER1, IMMP2L, CDKN2A, and CDKN2B26,44–47." (PMID 36163358, 2022). "Unlike IMMP2L, mGPDH is highly tissue specific and its impairment would not affect all tissues, which means that mitochondrial glycerol-3-phosphate dehydrogenase represents a suitable target for cancer therapy." (PMID 32717855, 2020).
neurological diseases (4 papers, 2014 to 2018). "In conclusion, our data suggest that partial deletions/duplications of IMMP2L gene may act as risk factors for neurological diseases and not only for GTS syndrome." (PMID 25478008, 2014). "We discuss the functions of the gene suggesting that IMMP2L may act as risk factor for neurological disease." (PMID 25478008, 2014).
central nervous system disorder (1 paper, 2020). A disease involving the central nervous system. "IMMP2L deficiency has been linked to mitochondrial dysfunction in the form of increased oxidative stress, a pathological feature common to several central nervous system disorders, and increased occurrence of cellular senescence, a pathological feature of neurodegeneration." (PMID 32265818, 2020).
IMMP2L also shares sentences with these, for which no sentence is quoted: schizophrenia (3 papers); psychiatric disorder (2); tumor (2); Anxiety (1); cardiomyopathy (1); erectile dysfunction (1); Leber congenital amaurosis (1); metabolic disease (1); psychomotor delay (1); thoracic aortic aneurysm (1); Warburg micro syndrome (1).